IGF1R (insulin like growth factor 1 receptor)
Diseases named in the same sentence as IGF1R in open-access papers (continued):
Sharing a sentence is not in itself a finding about the gene and the disease.
Adrenal insufficiency (2 papers, 2013 to 2025). Insufficient production of steroid hormones (primarily cortisol) by the adrenal glands. "No other pathogenic variants were found in genes associated with skeletal dysplasias (e.g., FGFR3, COL1A1), adrenal insufficiency (e.g., NR0B1, STAR), or growth retardation (e.g., IGF1R)." (PMID 41218602, 2025). "Similarly to Insr;Igf1r mutant embryos, Sf1 haploinsufficient mice exhibit adrenal insufficiency due to a severe reduction of adrenocortical precursors within the AGP, but show no change in the number of gonadal precursors." (PMID 23300479, 2013).
adrenocortical adenomas (2 papers, 2014 to 2025). "This study aimed to investigate IGF1R and IR expression and localisation, including the expression of IR isoforms, in ACC and adrenocortical adenomas (ACA), and their role in IGF2-driven proliferation." (PMID 40038716, 2025). "In particular, IGF1R expression was tested in ACC and compared to adrenocortical adenomas (ACA) and normal adrenals (NAG), with contrasting results." (PMID 40038716, 2025).
age (2 papers, 2023 to 2025). A temporal measurement of the time period elapsed since an identifiable point in the life cycle of an organism. "Insulin-like growth factor 1-Insulin-like growth factor 1 receptor (IGF-1-IGF-1R)signaling plays a vital role in regulating bone metabolism, and a decline in IGF-1 has been implicated in age-related bone loss." (PMID 37680888, 2023).
Arterial thrombosis (2 papers, 2017 to 2021). The formation of a blood clot inside an artery. "In conclusion, platelet miR-223 is a regulator of arterial thrombosis following endothelial injury through effects on vascular wall IGF-1R." (PMID 28487522, 2017).
Atrophy (2 papers, 2020 to 2023). Any weakening or degeneration, especially through lack of use. "We further defined the role of lncRNA H19/miR-675 in inducing muscle atrophy by targeting IGF1R, which provides clues for further elucidation of the mechanism of muscular atrophy and potential therapeutic targets." (PMID 37344807, 2023). "Insulin-like growth factor 1 receptor (IGF1R) and insulin receptor (INSR) were identified as target genes of miR-322 using luciferase reporter assays and played key roles in Dex-induced muscle atrophy." (PMID 32046161, 2020).
biliary tract cancer (2 papers, 2022 to 2025). "Our work is the first to comprehensively validate IGF1R upregulation across all CCA subtypes and link it to poor prognosis, underscoring the clinical significance of the IGF axis in biliary tract cancers." (PMID 41275311, 2025).
brain cancer (2 papers, 2020 to 2025). A primary or metastatic malignant neoplasm affecting the brain. "As the primary ligand for IGF1R, a phase I study of an IGF–methotrexate conjugate in treating advanced tumors expressing IGF1R, including brain cancer, has been set and completed (NCT02045368)." (PMID 39861756, 2025).
breast disease (2 papers, 2013 to 2015). "We extracted expression rates of carbonic anhydrase-IX (CAIX), glucose transporter-1 (GLUT1), C-X-C chemokine receptor type-4 (CXCR4), or insulin-like growth factor-1 receptor (IGF1R) in human breast disease, evaluated by immunohistochemistry." (PMID 24206539, 2013). "Furthermore, a multiantigen vaccine targeting Neu, IGFBP-2 and IGF1R was highly effective at preventing tumor progression in mice with preinvasive breast disease, whereas an individual vaccine was partially effective." (PMID 26173023, 2015).
carcinosarcoma (2 papers, 2015 to 2019). A malignant tumor composed of a mixture of carcinomatous and sarcomatous elements. "Less is known about the therapeutic role of insulin-like growth factor receptor-I (IGF-1R) inhibition in carcinosarcomas." (PMID 25962155, 2015).
colon adenoma (2 papers, 2011 to 2016). An adenoma that arises from the colon. "The acute increased IGF1R activity in colon adenomas following exposure to EGFR blockade raises the possibility of testing tumour specimens or circulating tumour cells for their initial response to drug." (PMID 21811251, 2011). "IGF-1R targeted imaging may be able to detect high risk polyps as suggested by our results and by previous reports that IGF-1R expression was detected in colon adenomas and became stronger as the degree of carcinogenesis progressed." (PMID 26731105, 2016).
colorectal adenocarcinoma (2 papers, 2024 to 2025). The most common type of colorectal carcinoma. "As a result, we examined a colorectal adenocarcinoma cell line with high basal expression of both PD-L1 and IGF-1R." (PMID 41184420, 2025). "Lastly, data suggested the Insulin Growth Factor 1 Receptor (IGF1R) cascade as one of the possible mechanisms involved in the effects induced by L. monocytogenes in the human colorectal adenocarcinoma cell line." (PMID 38491424, 2024).
craniosynostosis (2 papers, 2011 to 2019). Craniosynostosis is defined as the premature fusion of one or more cranial sutures leading to secondary distortion of skull shape resulting in skull deformities with a variable presentation. "The IGF1/IGF1R pathway is critical for normal bone growth and density and has been implicated in the etiology of craniosynostosis." (PMID 31442251, 2019). "Furthermore, mutations in IGF1R (insulin-like growth factor 1 receptor), another focal adhesion-related RTK, have been identified as potential causes of single-suture craniosynostosis." (PMID 22028906, 2011).
cyst (2 papers, 2017 to 2020). A sac-like closed membranous structure that may be empty or contain fluid or amorphous material. "Consistent with previous reports, we identified several inhibitors for IGF-1R with potent inhibitory effects on cyst swelling." (PMID 28644734, 2017). "We show that inhibition of several targets, including aurora kinase, CDK, Chk, IGF-1R, Syk, and mTOR, but, surprisingly, not PI3K, prevented forskolin-induced cyst swelling." (PMID 28644734, 2017).
diffuse midline glioma (2 papers, 2023). A diffuse glioma that arises from the midline structures of the central nervous system. "Linsitinib is an insulin-like growth factor 1 receptor (IGF-1R) inhibitor that can inhibit the growth of diffuse midline glioma with H3K27M mutations." (PMID 36845382, 2023). "Another study provided evidence that IGF1R/IR inhibitors could be emerging as an adjuvant of GD2 CAR T cells therapy for diffuse midline gliomas." (PMID 36635683, 2023).
ductal adenocarcinoma (2 papers, 2014 to 2020). "In one case of ductal adenocarcinoma that had received neoadjuvant treatment, the levels of IGF1R/PCNA signals went from moderate to none with an apparent decrease in nuclear IGF1R as determined by IHC." (PMID 32701997, 2020).
endometrial adenocarcinoma (2 papers, 2014). "These previous studies suggest that IGF-1, IGF-2 and IGF-1R expression levels are associated with the development of endometrial adenocarcinoma, highlighting the crucial role of IGF-1R function in EC and the importance of altered IGF-1R gene expression in the development of the malignant phenotype." (PMID 25289085, 2014). "Moreover, IGF1R and VEGF-C expressions were correlated in endometrial adenocarcinomas, and lymphatic vessel density was closely related to both." (PMID 24904527, 2014).
gastrinomas (2 papers, 2017 to 2024). "In gastrinomas, high levels of IGF-1 and its receptor (IGF-1R) were associated with tumor development, progression and aggressiveness." (PMID 39199391, 2024).
gestational diabetes (2 papers, 2020 to 2021). Carbohydrate intolerance first diagnosed during pregnancy. "Moreover, from these genes, ATG7, DICER1, IGF1R and RANBP2 may play an important role in the genesis and growth of gestational diabetes mellitus and might serve as aberrantly methylation‐based or expression of miRNA‐targeting biomarkers for precise diagnosis and treatment of GDM in the future." (PMID 33085184, 2020).
gout (2 papers, 2022 to 2024). A condition characterized by painful swelling of the joints, which is caused by deposition of urate crystals. "We explored association of the IGF1R rs6598541 SNP, identified as a genetic susceptibility variant for gout and serum urate levels, with cytokine production in human PBMCs." (PMID 38347000, 2024). "IGF1R is one of the loci associated with both urate levels and gout susceptibility in GWAS to date, and IGF-1-IGF-1R signaling is implicated in urate control." (PMID 38347000, 2024). "Also, we test the gout and urate-associated IGF1R rs6598541 polymorphism for association with the inflammatory capacity of mononuclear cells." (PMID 38347000, 2024). "In the present study we address the hypothesis that signaling via the IGF1R is associated to inflammation in gout." (PMID 38347000, 2024). "Also, the association of rs6598541 with IGF1R and protein expression and with ex vivo cytokine production levels after stimulation with gout specific stimuli was tested." (PMID 38347000, 2024). "Moreover, we assessed the association of the IGF1R rs6598541 SNP with IGF1R expression in circulating mononuclear cells and cytokine production capacity in patients with gout, asymptomatic hyperuricemia and normouricemic controls in an Eastern European population." (PMID 38347000, 2024). "IGF1R might be associated with activation of the NLRP3 inflammasome in gout." (PMID 35813212, 2022). "Thus, PNPLA3 and IGF1R variants might be linked to hyperuricemia and gout by affecting lipid metabolism and oxidative stress." (PMID 35813212, 2022). "Thus, both studies suggest that IGF1R variants might influence gout by regulating inflammation." (PMID 35813212, 2022). "However, we noticed an increased steady-state mRNA expression of IGF1R in unstimulated PBMCs from gout patients." (PMID 38347000, 2024). "In our study, when assessing freshly isolated PBMCs from patients with gout or controls we did not observe association of IGF1R gene expression with rs6598541." (PMID 38347000, 2024). "This study suggests that the role of IGF1R in gout is tissue-specific and may be more relevant in the control of urate levels rather than in inflammatory signaling in gout." (PMID 38347000, 2024). "In contrast, we could observe an increased steady-state mRNA expression of IGF1R in unstimulated monocytes originating from gout patients compared to normouricemic controls." (PMID 38347000, 2024). "Therefore IGF1R association to gout is most probably exerted via urate control rather than inflammatory mechanisms, via IGF1R, GLUT9 expression and activation, leading to urate reabsorbtion." (PMID 38347000, 2024). "We show that urate does not modulate the expression of IGF1R itself in vitro in PBMCs from healthy donors nor in vivo in PBMCs from gout patients." (PMID 38347000, 2024).
hepatic (2 papers, 2022 to 2023). "In normal condition, IGF-1R maintains low levels in the liver, but its expression will increase significantly when under pathological conditions (such as hepatitis); our results for IGF-1R verify this conclusion." (PMID 36430538, 2022).
Hypercholesterolemia (2 papers, 2019 to 2024). An increased concentration of cholesterol in the blood. "A vascular injury that is induced by hypercholesterolemia also increases Igf1r signaling, stimulating smooth muscle cell migration and division and contributing to accelerated atherosclerosis." (PMID 38961143, 2024).
infarction (2 papers, 2009 to 2023). A localised pathological necrosis of tissue resulting from obstruction of the blood supply usually by a thrombus, an embolus, or vascular torsion. "On the other hand, the expression of IGF-1R was increased in the 3 infarction zones of the dogs with ischemic cardiomyopathy, but not in the myocardium of dogs with tachycardiomyopathy." (PMID 19818143, 2009).
inflammatory myofibroblastic tumor (2 papers, 2021 to 2023). A multinodular intermediate fibroblastic neoplasm that arises from soft tissue or viscera, in children and young adults. "Recently, the novel fusion gene FN1-IGF1R, which has strong promoter activity for the kinase domain of IGF1R, has been identified in a subset of inflammatory myofibroblastic tumors." (PMID 34440844, 2021).
ischemia (2 papers, 2019 to 2021). A hypoperfusion of the BLOOD through an organ or tissue caused by a PATHOLOGIC CONSTRICTION or obstruction of its BLOOD VESSELS, or an absence of BLOOD CIRCULATION. "Knockdown of neuronal insulin-like growth factor 1 receptor (IGF-1R) exacerbates hypoxic injury and increases mortality in mice, and IGF-1R is required in order for IGF-1 to protect myocardial cell exposed to ischemia." (PMID 31246952, 2019).
ischemic stroke (2 papers, 2014 to 2022). A stroke disorder caused by obstruction of blood flow to the brain, due to thrombotic (local blood clot formation) or embolic (due to a blood clot or other material traveling from another site) event. "Other studies have reported that IGF-1 reduced brain infarct volume and protected neurons via IGF-1R in the rat brain with ischemic stroke." (PMID 35883879, 2022).
Kawasaki disease (2 papers, 2024 to 2025). A rare inflammatory disease characterized by an acute febrile, systemic, self-limiting, medium-vessel vasculitis primarily affecting children. "Regarding cardiovascular diseases, it has been reported that miR-197-3p induces damage in human coronary arterial endothelial cells by regulating target genes such as TIMP3 and IGF1R, especially in Kawasaki disease." (PMID 41009512, 2025). "MIR-197-3p regulates the proliferation and migration of Kawasaki disease endothelial cells by targeting IGF1R and Bcl-244." (PMID 38600259, 2024).
kidney damage (2 papers, 2017 to 2025). "Overall, our findings demonstrate that intermittent exercise alleviates MI-associated kidney damage through IGF-1/IGF-1R/PI3K/AKT pathway activation and the suppression of pathological oxidative, inflammatory, and apoptotic processes." (PMID 41488924, 2025).
kidney stone (2 papers, 2023 to 2025). "Second, although we observed changes in IGF1R expression in human samples, the sample size was relatively small, and larger-scale clinical studies are needed to further validate the role of IGF1R in human nephrolithiasis." (PMID 39744436, 2025). "Although direct studies on IGF1R in kidney stone-related EMT are scarce, previous researches have emphasized the significance of EMT in renal diseases." (PMID 39744436, 2025). "Future research should investigate IGF1R's interactions with other signaling pathways to fully comprehend its role in the pathophysiology of nephrolithiasis." (PMID 39744436, 2025). "In the rat kidney stones model, IGF1R was significantly downregulated and had a negative relationship with miR-184." (PMID 38154105, 2023). "By understanding the role of IGF1R in EMT, it may be possible to develop targeted interventions that mitigate the progression of kidney stone formation and associated complications." (PMID 39744436, 2025). "Given the well-established role of IGF1R in influencing STAT3 phosphorylation, this study focused on the regulation of downstream LDHA by JAK2/STAT3 signaling axis and its role in kidney stone formation." (PMID 39744436, 2025). "To elucidate the mechanisms by which IGF1R mediates metabolic disturbances and EMT induced by kidney stone damage, we performed a combined analysis of transcriptomics and untargeted metabolomics in a COM-induced cell injury model." (PMID 39744436, 2025). "The potential implications of IGF1R in kidney stone-related EMT could extend beyond basic research, offering novel therapeutic targets for the prevention and treatment of kidney stone disease." (PMID 39744436, 2025).
large cell carcinoma (2 papers, 2010 to 2011). A malignant epithelial neoplasm composed of large, atypical cells. "Proliferation of the large-cell carcinoma cell line A549, which exhibited moderately activated HER1 and IGF-1R pathways, was inhibited by the PI3K inhibitor BEZ-235 and by the IGF-1R inhibitor BMS-536924 and weakly by the MEK inhibitor PD-325901." (PMID 22091388, 2011). "The large-cell carcinoma cell line A549 exhibited a moderate activation of the HER1 and IGF-1R pathways with a low activation of the c-MET and HER2 pathways, whereas the metastatic large-cell carcinoma cell line H460 showed only a very low activation of the IGF-1R pathway." (PMID 22091388, 2011).
lung squamous cell carcinoma (2 papers, 2009 to 2018). "In our IHC studies, a majority of squamous cell lung cancers displayed high levels of IGF-1R expression." (PMID 19806209, 2009).
mucinous lung adenocarcinoma (2 papers, 2015 to 2020). "Inhibition of insulin-like growth factor-1 receptor (IGF-1R) could overcome the resistance of mucinous lung adenocarcinoma to gefitinb." (PMID 26356816, 2015).
myeloid leukemia (2 papers, 2013 to 2015). A clonal proliferation of myeloid cells and their precursors in the bone marrow, peripheral blood, and spleen. "In the present study, we used this experimental approach to show that the natural naphthoquinone shikonin strongly deregulates the IGF1R-Akt-mTOR signaling cascade in U937 myeloid leukemia cells." (PMID 23861714, 2013).
myopia (2 papers, 2019 to 2022). "We demonstrated that over-expression of HOXA9 in RPE cells could increase pro-myopia substances including TGF-β, FGF2, IGF1R and MMP2." (PMID 30674274, 2019).
neuropathy (2 papers, 2017 to 2025). A disorder affecting the nervous system that manifests with pain, tingling, numbness, and/or muscle weakness. "On the contrary, a heterozygous missense variant in KIF1B was proposed to cause neuropathy by impairing insulin‐like growth factor 1 receptor (IGF1R) in a recent study." (PMID 39776111, 2025).
osteoarthritis (2 papers, 2020 to 2021). A noninflammatory degenerative joint disease occurring chiefly in older persons, characterized by degeneration of the articular cartilage, hypertrophy of bone at the margins and changes in the synovial membrane. "Hsa_circ_0045714 could regulate chondrocyte to synthesize extracellular matrix through miR-193b targeting IGF1R in osteoarthritis." (PMID 33425899, 2020). "Within tier 1, ten candidates have previously been studied in clinical trials of efficacy or in cohort studies of osteoarthritis (six arising from new signals: PPARD, NR3C1, VDR, MAPK14, IGF1R, and CHST3)." (PMID 34450027, 2021).
paraganglioma (2 papers, 2020 to 2024). A benign or malignant neoplasm arising from paraganglia located along the sympathetic or parasympathetic nerves. "Of note, overexpression of the related insulin-like growth factor 1 receptor (IGF-1R) has been associated with malignancy in familial pheochromocytomas and paragangliomas." (PMID 39619326, 2024). "The aim of this study was to investigate the expression of Snail, galectin-3, and IGF1R in benign and malignant pheochromocytoma and paraganglioma (PPGL) and explore their role in the diagnosis of malignant PPGL." (PMID 32190664, 2020).
placental insufficiency (2 papers, 2022 to 2025). Failure of the placenta to deliver an adequate supply of nutrients and oxygen to the fetus. "Based on our results, we propose that MAP3K4 plays a critical role in the IGF1R/IR and Akt signaling pathway in TS cells and placenta, and MAP3K4 KI results in FGR caused by placental insufficiency." (PMID 35921893, 2022). "Growth restriction is often characterised by defects in IGF-1/Insulin-like Growth Factor 1 Receptor (IGF1R) signalling and placental insufficiency." (PMID 41258474, 2025).
Pleural effusion (2 papers, 2015 to 2022). The presence of an excessive amount of fluid in the pleural cavity. "In order to evaluate heterogeneity among NSCLC tumors, we quantitated the expression and phosphorylation levels of common RTKs, such as the HER family, MET and IGF-1R, in tumor cells isolated from pleural effusion and/or fine needle aspirations (FNAs)." (PMID 26439803, 2015).